GAST (gastrin)
Diseases named in the same sentence as GAST in open-access papers (continued):
Sharing a sentence is not in itself a finding about the gene and the disease.
gastric cancer (continued). "In some developed countries, H. pylori IgG, pepsinogens (PGs), and gastrin-17 (G-17) have been studied as non-invasive serological evaluation of gastric cancer and precancerous gastric lesions and have been suggested a variety of cut-off values." (PMID 36251649, 2022). "Since gastrin has been shown to stimulate growth of human gastric cancer, researchers have been studying means to block gastrin’s actions in gastric cancer using CCK-BR antagonists and their use in human trials reviewed." (PMID 34926305, 2021). "For example, in gastric cancer, high expression of gastrin increases HIF-1α/VEGF expression and promotes tumour angiogenesis." (PMID 34349170, 2021). "The results showed that the expression of IκB-α was significantly upregulated, while p-IκB-α and NF-κB-p65 were significantly downregulated after knockdown of gastrin in gastric cancer cells (P < 0.05)." (PMID 33937399, 2021). "In this review based upon experience of gastric cancer where gastrin is central in the pathogenesis, it is argued that oxyntic atrophy—and not metaplasia as postulated by Correa—is the central precancer change in gastric mucosa." (PMID 34202596, 2021). "Immunocytochemistry revealed endogenous gastrin peptide expression in both NCC and YTN gastric cancer cells suggesting that these gastric cancer cells produce their own gastrin peptide to stimulate growth via the CCK-BR in an autocrine fashion." (PMID 34926305, 2021). "Gastrin-interfering cell line was constructed by stably transfecting gastrin-specific pshRNA plasmid to gastric cancer cell line BGC-823." (PMID 33937399, 2021). "We unexpectedly detected that knockdown of gastrin resulted in the overexpression of several mitochondrial respiratory chain-related proteins and elevated mitochondrial membrane potential in gastric cancer cells." (PMID 33937399, 2021). "At present, studies have found that gastrin level has a strong relationship with the development of gastric cancer." (PMID 35096975, 2021). "In the current investigation, we demonstrated using two murine gastric cancer cell lines and a human tissue microarray that the gastrin: CCK-BR signaling pathway is important in stimulating growth of gastric cancer." (PMID 34926305, 2021). "To date, the role of gastrin in inhibiting apoptosis of gastric cancer cells has been fully elucidated; however, the underlying mechanism remains to be further investigated." (PMID 33937399, 2021). "We previously showed that CCK-BRs are expressed on several human gastric cancer cell lines and that gastrin-stimulated growth in vitro was only blocked by the selective CCK-BR antagonist, L265,260." (PMID 34926305, 2021). "They found that gastrin can inhibit the proliferation of poorly differentiated gastric cancer cells and enhance the inhibitory effect of cisplatin on gastric cancer by activating erk-p65-mir 23a/27a/24 axis." (PMID 35096975, 2021). "In the present review we will repeat and strengthen the arguments in favour of the role of gastrin in H. pylori carcinogenesis and then focus on the different types of gastric polyps as precursors of gastric cancer." (PMID 34207192, 2021). "In a gastric cancer cell line, Hdc gene expression is activated by gastrin signaling through gastrin‐responsive elements in the promoter region (Ai, Liu, Langlois, & Wang, 2004)." (PMID 32394600, 2020). "Overexpression of gastrin is an important factor in the development of gastric cancer as discussed here." (PMID 32117120, 2020). "Together with sex hormones, oestrogens causing breast cancer and androgens cancer of the prostate, the role of gastrin in gastric cancer are examples of hormonal carcinogenesis." (PMID 33266504, 2020). "G17DT was shown to elicit functional antibodies against gastrin with safe and well-tolerated profile in 52 patients with gastric carcinomas, with the exception that two patients suffered significant adverse reactions." (PMID 32210918, 2020).
gastric cancer (continued). "Combined efficacy of sPGA with H. pylori antibody and/or gastrin-17 has been indicated for the prediction of gastric cancer and CAG, and it is mainly used in Europe (as panel test)." (PMID 31083485, 2019). "Long-term hypergastrinemia results in gastric neoplasia of variable malignancies, implying that gastric hypoacidity resulting in increased gastrin release will induce gastric neoplasia, including gastric cancer." (PMID 31108898, 2019). "Gastrin is a well-known growth-promoting factor for gastric cancer cells, and our previous report demonstrated that the gastrin receptor was detected in gastric cancer cells." (PMID 31197475, 2019). "In a follow-up, patients with hypergastrinemia at the initial blood sampling developed gastric carcinomas more often than those with normal gastrin values." (PMID 31108898, 2019). "It has been reported that CacyBP/SIP localizes to the cytoplasm and nucleus, and nuclear translocation of CacyBP/SIP can be induced by cell proliferation of gastric cancer, which is promoted by gastrin." (PMID 30234028, 2018). "Two studies demonstrated that complex gastric microbiota can promote H. pylori-induced gastric cancer by hastening the onset of malignancy and promoting tumor progression using hypergastrinemic insulin-gastrin (INS-GAS) transgenic mouse model." (PMID 30619779, 2018). "In order to further explore the effects of gastrin on gastric cancer cells, further studies are needed." (PMID 28980157, 2018). "The role of gastrin in gastric cancer cannot, however, be overlooked as some studies have demonstrated hypergastrinemia in patients with these cancers." (PMID 28980157, 2018). "The same markers were also expressed in a proportion of adenocarcinomas supporting the view that gastrin is important in the development of gastric cancer." (PMID 28980157, 2018). "The same markers were also expressed in a proportion of adenocarcinomas of the diffuse and intestinal type, incriminating gastrin in the development of gastric cancer." (PMID 28980157, 2018). "In some patients with gastric carcinoma, there are elevated gastrin levels, incriminating gastrin as a driving force in the development of these cancers." (PMID 28980157, 2018). "These mapped with high statistical significance to ten canonical signaling pathways, all of which were less active in low DOK6 gastric cancers: gastrin-CREB, NGF, PDGF, EGFR, ERKs, ERBB4, FGFR2, RAS, VEGFR2 and RAF/MAP kinase." (PMID 29872697, 2017). "The few studies that have examined gene expression profiles in mouse model of gastric cancer have used the insulin-gastrin (INS-GAS) transgenic gastric cancer mouse model." (PMID 28201999, 2017). "In gastric cancer, gastrin is responsible for not only inducing acid secretion but also stimulating a number of oncogenic pathways, such as cyclin D1 and β‐catenin pathways 22, to induce cancer progression." (PMID 28781948, 2017). "Gastric cancer cells overexpress gastrin as a way to remodel microenvironment to facilitate the outgrowth and metastases." (PMID 28781948, 2017). "Given the anticancer efficacy of curcumin, it is possible that curcumin also regulates gastrin expression in gastric cancer." (PMID 28781948, 2017). "The CCKBR ligand gastrin, which is also highly expressed by PDAC cells, can stimulate growth of pancreatic, colon, and gastric cancer, and gastrin-stimulated PDAC cell growth can be blocked with a CCKBR-specific antagonist." (PMID 27754762, 2017). "INS-GAS mice have also been used to investigate the effect of gastrin on gastric cancer development." (PMID 27713138, 2017). "This confirms that curcumin lowers gastrin secretion to elevate gastric fluid pH, which inhibits gastric cancer progression." (PMID 28781948, 2017). "In gastric cancer, curcumin suppresses gastrin‐mediated acid secretion, which inhibits gastric cancer progression." (PMID 28781948, 2017).
gastric cancer (continued). "Both gastrin and sCLU alone promoted an anti-apoptotic effect on gastric cancer cells, and it is noteworthy that gastrin and sCLU in combination enhanced survival even further, particularly on early apoptosis signaling." (PMID 28902909, 2017). "Here, we corroborated that curcumin potently inhibits gastric cancer growth both in vitro and in vivo, accompanied by significant gastrin downregulation and hypoacidity in stomach." (PMID 28781948, 2017). "Western blot analysis of gastric cancer cells in the apoptotic gene capase‐3 inhibition of gastrin confirmed that curcumin exerts its antitumor effects by promoting apoptosis." (PMID 28781948, 2017). "The Asia Pacific Working Group on Gastric Cancer recommends the combined use of H. pylori serology, and serum gastrin-17 and pepsinogen concentrations, and the presence of histological intestinal metaplasia to screen gastric cancer." (PMID 28968998, 2017). "While gastrin was abundantly secreted by gastric cancer cells, gastrin level in the medium of curcumin‐treated cells was much lower than that in untreated cells." (PMID 28781948, 2017). "Similar to proglumide, curcumin acts as an antagonist to gastrin and curcumin demonstrated superior anticancer efficacy in gastric cancer compared to proglumide." (PMID 28781948, 2017). "In gastric cancer cell lines, gastrin increased secretion of clusterin, and both gastrin and secretory clusterin promoted survival after starvation- and chemotherapy-induced stress." (PMID 28902909, 2017). "Previous in vitro experiments using several gastric cancer cell lines showed that oncogenic H- and K-Ras activate the gastrin promoter, thus suggesting the importance of various Ras isoforms on gastrin expression." (PMID 29379775, 2017). "In this review, we will focus on the role of gastrin in the etiology of gastric cancer and at the same time give an explanation of the decline in frequency." (PMID 28144230, 2017). "miR-146a expression is also up-regulated in the stomach of gastrin-knockout mice and also in 73% of tested gastric cancers." (PMID 27323780, 2016). "Previous study has reported that gastrin acting on CCK-BR induces cyclooxygenase-2 expression through JAK2/STAT3/PI3K/Akt pathway in human gastric cancer cells." (PMID 27518872, 2016). "In the present study, the effect of gastrin on Tfs that bind to the cis-acting regulatory elements in introns of the Reg1 gene in gastric cancer cells was also explored by Southwestern blotting." (PMID 25621062, 2015). "Increased expression of gastrin has been demonstrated in the progression of intestinal gastric cancer." (PMID 25621062, 2015). "The current study explores the molecular mechanism of gastrin-regulated Reg1 expression in human gastric cancer cells." (PMID 25621062, 2015). "Patients with gastroesophageal adenocarcinoma or untreated metastatic unresectable gastric cancer received G17DT (Aphton) vaccination containing 9-amino-acid epitope derived from the aminoterminal sequence of gastrin-17 and cisplatin plus 5-fluorouracil." (PMID 26579545, 2015). "Gastrin treatment decreased pHi of human gastric cancer cells in a manner correlating with the increased expression of SLC4A2." (PMID 24795638, 2014). "Since cell migration and invasion are characteristics of the progression of gastric cancer, and processes known to be regulated by gastrin, we wanted to address the role of SIK1 in gastrin-mediated responses." (PMID 25384047, 2014). "In this study we have elucidated the signaling events that lead to IL1B-mediated repression of gastrin expression through NFkB activation in gastric carcinoma cells." (PMID 24009751, 2013). "2/3 of the human gastric adenocarcinomas as well as in the gastrin KO mouse model of gastric cancer." (PMID 22992343, 2012). "The expression of miR-146a was evaluated by quantitative PCR (qPCR) and found up-regulated in the gastrin knockout mice, a mouse model of gastric cancer, and in 73% of investigated human gastric adenocarcinomas." (PMID 22992343, 2012).
gastric cancer (continued). "In this study, we address the importance of microRNAs in gastric cancer taking advantage of the Gastrin knockout mouse model and H. pylori infection of wild type mice." (PMID 21418558, 2011). "In order to identify microRNAs deregulated during the development of gastric cancer, we examined miRNAs expression profiles in gastric neoplasias from Gastrin knockout mice using miRNA microarrays." (PMID 21418558, 2011). "Using the Gastrin knockout mouse model for gastric cancer, we identify 20 deregulated microRNAs of which 3 were more than 2-fold deregulated relative to their levels in normal gastric mucosa." (PMID 21418558, 2011). "Results from transgenic mice show that mice overexpressing the amidated form of gastrin have increased proliferation of gastric mucosa, which can synergize with Helicobacter infection leading to the development of invasive gastric cancer." (PMID 20637111, 2010). "All these studies indicate an important role of gastrin-and its receptor system in mediating gastric cancer." (PMID 20637111, 2010). "Despite an apparent connection of gastrin in gastric cancer progression, the detailed mechanism by which gastrin mediates its effects is still unclear." (PMID 20637111, 2010). "Other workers have also observed that Cox-2 inhibition influenced gastrin expression in an in vitro colorectal cancer model and also in H. pylori positive gastric cancer patients." (PMID 19317916, 2009). "Therefore, the authors believe that long-term use of PPIs can lead to an increase in gastrin, the formation of hypergastrinemia, and mediate the development of gastric cancer or gastric neuroendocrine tumors via the gastrin-ECL cell axis." (PMID 40660564, 2025). "Conversely, PPIs could also result in the under-secretion of gastrin and prevent the growth of gastric cells that offer protection against gastric cancer." (PMID 38610738, 2024). "Another study indicated that serum gastrin levels may serve as a predictive marker for gastric cancer when comparing gastric cancer cases with non-gastric cancer cases." (PMID 39518740, 2024). "Besides, in primary gastric epithelial cells, helicobacter and gastrin stimulated the expression of REG1α and accelerated the progression of gastric cancer." (PMID 37626036, 2023). "We found that the forced gastrin could promote the proliferation, migration, and invasion of gastric cancer cells by upregulating the expression of MMP-2 and VEGF." (PMID 34976177, 2022). "Many experiments have shown the proliferation-promoting effects of gastrin in gastric cancer cells." (PMID 34976177, 2022). "Limited by the low dimension of sample data, other biomarkers related to gastric cancer such as gastrin, MG7-Ag (gastric carcinoma-associated MG7-Ag) were not included in this study." (PMID 36526664, 2022). "Therefore, commercially available gastrin 17 (defined as G17) was used to treat gastric cancer cell lines in vitro to assess the effects of gastrin." (PMID 34976177, 2022). "Whether gastrin could affect the production of ROS by modulating the oxidative respiratory chain of mitochondria in gastric cancer cells and thus affect cancer cell apoptosis are unclear." (PMID 33937399, 2021). "Overexpressed gastrin is reported to promote oncogenesis and development of gastric cancer by inhibiting apoptosis of cancer cells; however, the underlying mechanism remains unclear." (PMID 33937399, 2021). "In this study, we found that knockdown of gastrin in gastric cancer cells could result in the overexpression of COX17, COX5B, and ATP5J proteins, elevation of mitochondrial membrane potential, and reduction of ROS production in gastric cancer cells." (PMID 33937399, 2021). "On the other hand, the intestinal type of gastric cancer may develop from the stem cell where gastrin also stimulates proliferation either by a possible gastrin receptor or via Reg released from the ECL cell." (PMID 34948181, 2021).
gastric cancer (continued). "Human gastric cancer epithelial cells were positive for CCK-BR immunoreactivity implying that the administration of PAS to human subjects would also decrease activation of this receptor by neutralizing gastrin." (PMID 34926305, 2021). "Gastrin may also stimulate growth of gastric cancer when blood gastrin levels are increased from chronic use of high dose proton pump inhibits (PPIs), achlorhydria or Helicobacter pylori infection." (PMID 34926305, 2021). "Immunocytochemistry revealed endogenous gastrin expression within the gastric cancer cells suggesting that gastric cancer may regulate its own growth by an autocrine mechanism." (PMID 34926305, 2021). "Indeed, we showed that a vaccine that targets gastrin can inhibit growth of gastric cancer in mice and prevent metastases." (PMID 34926305, 2021). "In addition, it is proved that gastrin functions as a stimulator of the metastasis of gastric carcinoma through the β-catenin-TCF4 pathway." (PMID 33937399, 2021). "The PPI-induced, growth-promoting effects of gastrin, on tumors in the stomach, increasingly appears to affect gastric cancers as well as gastric carcinoids, and may well extend to cancers in other organs." (PMID 31963924, 2020). "In another open-label, multinational, and multicenter phase II study, sixty-five of 94 advanced gastric cancer patients were successfully vaccinated with G17DT in terms of anti-gastrin antibody production and showed longer time-to-progression and median survival compared to control patients." (PMID 32210918, 2020). "Together with the main regulator of the ECL cell, gastrin, CgA may be used in the diagnoses of autoimmune chronic atrophic gastritis, which is the main factor in gastric cancer whether induced by H. pylori or autoimmunity." (PMID 33266504, 2020). "Our data and those of previous studies suggest that gastrin differentially influences the development of gastric cancers and NETs, with the former likely originating from gastric stem cells and the latter from ECL cells, although the two cell types express the same gastrin receptor." (PMID 33066474, 2020). "We hypothesize that diminished gastrin levels may contribute to the restoration of malignant morphology of gastric cancer tissue, including the appearance of ELA." (PMID 31197475, 2019). "Detection of intracellular signal substances will not necessarily prove that gastrin has a positive trophic effect on gastric cancer cells; thus, biological effects of gastrin are better demonstrated by confirming an inhibitory effect of a CCKBR antagonist on such tumors in vivo." (PMID 28980157, 2018). "Gastrin inhibits gastric cancer growth through activating the ERK-P65-miR23a/27a/24 axis." (PMID 29866191, 2018). "Whether gastrin has a dominating role in the development of gastric carcinoma has been under debate." (PMID 28980157, 2018). "Based upon our results it seems that the major part of gastric carcinomas of diffuse type may develop from the ECL cells secondary to long-term hyper-stimulation with gastrin." (PMID 30567376, 2018). "Thus, gastrin seems to be involved in most cases of gastric carcinomas occurring anally/distally to the cardiac region, where Hp seems not to play any role." (PMID 30567376, 2018). "CREB is activated via MAPK in gastric cancer cells upon gastrin stimulation." (PMID 29237412, 2017). "We showed that curcumin reduces gastrin secretion by gastric cancer cells." (PMID 28781948, 2017). "Therefore, in this study, we sought to correlate curcumin to the gastrin‐mediated gastric acid secretion and investigate how this inhibits gastric cancer." (PMID 28781948, 2017). "Furthermore, cisplatin and gastrin made gastric cancer cells express and secrete CLU, leading to increased survival and possibly treatment resistance." (PMID 28902909, 2017).